SSTR1 (somatostatin receptor 1)
Description:
Receptor for somatostatin with higher affinity for somatostatin-14 than -28. This receptor is coupled via pertussis toxin sensitive G proteins to inhibition of adenylyl cyclase. In addition it stimulates phosphotyrosine phosphatase and Na(+)/H(+) exchanger via pertussis toxin insensitive G proteins.
Synonyms: SS-1-R; SS1-R; SS1R; SST1; SRIF-2
Tractability: Small molecule: a structure with a bound ligand is known; a high-quality ligand is known; it belongs to a druggable protein family. Antibody: its Gene Ontology location is reachable by antibodies, with high confidence; UniProt places it where antibodies can reach, with medium confidence; UniProt predicts a signal peptide or a membrane-spanning region. PROTAC: a small molecule that binds it is known. Other modalities: an approved drug acts on it.
Target class: Peptide receptor (family A GPCR); Membrane receptor; Short peptide receptor (family A GPCR); Family A G protein-coupled receptor; Somatostatin receptor
Chemical probes: CHEMBL556949, CHEMBL71723
Gene: Protein-coding gene on chromosome 14 (38,207,904 to 38,213,067, forward strand). Ensembl gene ENSG00000139874.
Subcellular location: Cell membrane
Subcellular location (Human Protein Atlas): Vesicles
Pathways (Reactome):
Signal Transduction: G alpha (i) signalling events; Peptide ligand-binding receptors
Gene Ontology:
Molecular function: protein binding; somatostatin receptor activity; neuropeptide binding; G protein-coupled receptor activity
Biological process: cellular response to estradiol stimulus; G protein-coupled receptor signaling pathway, coupled to cyclic nucleotide second messenger; negative regulation of cell population proliferation; neuropeptide signaling pathway; cerebellum development; forebrain development; G protein-coupled receptor signaling pathway; response to starvation; somatostatin signaling pathway; spermatogenesis
Cellular component: neuron projection; plasma membrane; membrane
Genetic constraint (gnomAD): Loss-of-function variants: 10 observed, 21 expected, observed/expected ratio (o/e) 0.48, 90% interval 0.29 to 0.81. The upper end of that interval is the gene's LOEUF score, 0.81, which puts it in group 3 of 6, group 1 being the genes least tolerant of losing a copy. Missense variants: 494 observed, 557.31 expected, observed/expected ratio (o/e) 0.89, 90% interval 0.82 to 0.95. Synonymous variants: 267 observed, 239.59 expected, observed/expected ratio (o/e) 1.11, 90% interval 1.01 to 1.23.
Homologues: Orthologues: chimpanzee SSTR1 (100% identical), macaque SSTR1 (100% identical), dog SSTR1 (99% identical), guinea pig SSTR1 (99% identical), rabbit SSTR1 (99% identical), mouse Sstr1 (99% identical), rat Sstr1 (97% identical), pig SSTR1 (91% identical), zebrafish sstr1a (73% identical), tropical clawed frog sstr1 (72% identical), Caenorhabditis elegans trhr-1 (22% identical), Drosophila melanogaster Rh7 (21% identical). Paralogues in human: SSTR4 (58% identical), SSTR2 (43% identical), SSTR5 (43% identical), SSTR3 (42% identical), OPRD1 (36% identical), OPRM1 (34% identical), OPRK1 (34% identical), OPRL1 (33% identical), NPBWR2 (30% identical), NPBWR1 (29% identical), KISS1R (26% identical), UTS2R (23% identical), and 5 more.
Diseases named in the same sentence as SSTR1 in open-access papers:
SSTR1 is named in the same sentence as 93 diseases in open-access papers, as found by Europe PMC text mining. Sharing a sentence is not in itself a finding about the gene and the disease. The quoted sentences say what the papers report.
prostate carcinoma (14 papers, 2017 to 2025). A carcinoma that arises from epithelial cells of the prostate gland. "SSTR1 have been reported to be the most prominent candidates of biomarkers associated with aggressive prostate cancer phenotype." (PMID 36704352, 2022). "SSTR1 has also been reported in prostate cancer as a diagnostic marker and as a therapeutic target." (PMID 38203605, 2023). "SSTR1 is associated with various cancers, such as prostate cancer and gastric cancer." (PMID 35602512, 2022). "We identified a novel gene risk panel comprising six genes (SSTR1, CA14, HJURP, KRTAP5-1, VGF, and COMP) for prostate cancer risk classification." (PMID 40592939, 2025). "For prostate cancer, SSTR1 was found to be the primary receptor expressed in the case of prostate neoplasias, amongst 80 different samples; this overexpression of SSTR1 has been also documented by other researchers." (PMID 39329930, 2024). "Other targets that have been associated with prostate cancer metastasis (or progression) include BIRC5/survivin, EZH2, TOP2A, HMMR, LPL, and SSTR1." (PMID 34680307, 2021). "SSTR1 was widely related to the progression of various cancers, and also functions as a prognostic marker in prostate cancer." (PMID 31861273, 2019). "In addition to that, SSTR1 plays a significant role in the onset and progression of prostate cancer." (PMID 36704352, 2022). "SSTR2 is preferably expressed in the normal prostate, while SSTR1 and SSTR5 are expressed in prostate cancer." (PMID 33586406, 2021).
adenoma (9 papers, 2005 to 2024). A neoplasm arising from the epithelium. "Another study found that TSH-secreting adenomas express SSTR1, 2A, 3, and 5 mRNA, especially SSTR2A." (PMID 39202532, 2024). "Our aim is to examine the immunohistochemical expression of somatostatin receptor 1–5 in parathyroid typical adenomas, atypical adenomas and carcinomas." (PMID 31336364, 2019). "Rat GC tumors display a somewhat similar expression pattern of Sstr subtypes, but Sstr1 expression in GC tumors was higher compared to what it has been observed in human GH-secreting adenomas." (PMID 26549306, 2015). "SSTR1 was highly upregulated in invasive adenoma (log2FC = 9.14, p = 0.005) as well as the adhesion receptor ADGRG2 (log2FC = 5.26, p = 0.026), the serotonin receptor HTR4 5 (log2FC = 3.68, p = 0.007) and the prostaglandin receptor PTGER2 (log2FC = 3.06, p = 0.038)." (PMID 35203352, 2022). "Nevertheless, our mRNA expression data confirmed the relatively low expression of SSTR1 in GH‐producing adenomas, in agreement with previous studies 10, 12, which could explain our inability to detect SSTR1 by IHC." (PMID 29266696, 2018). "However, in that study, SSTR1 expression was found in a minority of these adenomas and was predominantly localized to the cytoplasm with occasional membranous localization." (PMID 29266696, 2018). "Compared to a normal adrenal gland, ACC revealed an increase in almost all SSTR, while only some aldosterone-producing adenomas over-expressed SSTR3 and SSTR1." (PMID 37185426, 2023). "In 1994, Greenman and Melmed analyzed SSTR 3, SSTR4, and SSTR5 in 33 pituitary adenomas and SSTR1 and SSTR2 in 27 pituitary adenomas using RT-PCR, including 2 and 3 ACTH-producing adenomas, respectively." (PMID 30627156, 2018). "There was a negative correlation between SSTR1 expression and adenoma size (r = −0.36, Spearman FDR adjusted P = 0.04)." (PMID 29266696, 2018). "Moreover, SSTR1-expressing cells from GH- and PRL-secreting adenomas and medullary thyroid cancer exhibited inhibition of hormone secretion in addition to reduced cell viability in response to SSTR1-specific agonist." (PMID 16018813, 2005). "In light of the increased expression of SSTR1 in nonfunctioning adenomas, as presented in this study, pasireotide may also be a possible treatment option in this frequent adenoma subgroup." (PMID 30627156, 2018).
meningioma (8 papers, 2021 to 2025). A generally slow growing tumor attached to the dura mater. "In feline meningiomas (n = 12), RNA expression of SSTR1, SSTR4, SSTR5 and SSTR2 was detected in 91%, 46%, 46% and 36% of samples, respectively; SSTR3 was not expressed." (PMID 39011594, 2024). "The recurrent meningioma exhibited membranous SSTR1 staining, whereas SSTR2 showed additional nuclear staining." (PMID 39011594, 2024). "Expression rate in canine and feline meningioma was slightly higher than the detection rate in human studies, ranging between 62%–98% and 81%–100% for SSTR1 and SSTR2, respectively." (PMID 39011594, 2024). "The recurrent meningioma expressed SSTR1, which the first meningioma also expressed, and additionally expressed SSTR5." (PMID 39011594, 2024). "In canine meningiomas (n = 7), RNA expression of SSTR1, SSTR2 and SSTR5 was detected in all samples; SSTR3 RNA expression was detected in only 33% of samples." (PMID 39011594, 2024). "We report a significantly higher expression of SSTR1, -2 and -5 in grade 2 meningiomas, compared with WHO grade 1 tumors." (PMID 34830858, 2021). "The predominantly non-immunoreactive normal meningeal tissue supports a general upregulation of SSTR1 and -5 in most meningiomas." (PMID 34830858, 2021). "In this study, we found an overall high expression of SSTR1, -2 and -5 in human meningiomas with both manual and digital scoring." (PMID 34830858, 2021). "• Feline meningiomas exhibited SSTR1, SSTR4, SSTR5 and SSTR2 expressions." (PMID 39011594, 2024). "On average, 87.6% of meningiomas expressed this latter (95% CI: 79.1; 96.1) versus 54% for the SSTR-1 subtype (95% CI: 0; 100), 57.1% for the SSTR-3 subtype (95% CI: 24.5; 89.7), 60.3% for the SSTR-4 subtype (95% CI: 26.8; 93.8), and 63.1% for the SSTR-5 subtype (95% CI: 12.2; 100)." (PMID 36765937, 2023). "IHC of 7 canine and 12 feline meningiomas utilizing antibodies against SSTR1 and SSTR2 revealed immunoreactivity in all feline and canine meningiomas." (PMID 39011594, 2024). "The distribution of SSTR1, SSTR4 and SSTR5 in feline meningiomas was similar to that of human meningiomas." (PMID 39011594, 2024). "In this investigation, SSTR1 and SSTR2 detection rates in IHC were 100% in meningioma samples from both species." (PMID 39011594, 2024). "Membranous and cytoplasmic staining were observed most frequently (SSTR1, 43%; and SSTR2, 71%) in canine meningiomas." (PMID 39011594, 2024). "This large cohort also showed strong expression of SSTR1 and SSTR5 and different expression patterns within various clinical subgroups, such as neurofibromatosis type 2 and WHO grades II and III meningiomas." (PMID 35566491, 2022). "Our recent retrospective analysis has demonstrated that SSTR1 and SSTR5 are also highly expressed in many meningiomas." (PMID 35566491, 2022). "Currently, no data are available on the correlation between SSTR1 expression in canine and feline meningioma and therapeutic success." (PMID 39011594, 2024). "• RNA analysis showed SSTR1, SSTR2 and SSTR5 expressions in canine meningiomas." (PMID 39011594, 2024).
colon carcinoma (7 papers, 2016 to 2025). "Furthermore, SST has been shown to control the feedback system between colon neuroendocrine cells and colon cancer stem cells through SSTR1 to regulate stem cell quiescence and proliferation." (PMID 38203605, 2023). "SST and SSTR1-5 are well expressed in HT29 cells derived from low grade differentiated tumor whereas cell obtained from high grade and undifferentiated colon cancer namely SW480 are devoid of SST and SSTR5." (PMID 38203605, 2023). "Indeed, our study shows that SSTR1+ and GLP-2R+ cells produce their own corresponding ligands in normal crypts as well as in colon carcinomas (SST and GLP-2, respectively)." (PMID 33112876, 2020).
gastric cancer (6 papers, 2015 to 2022). A primary or metastatic malignant neoplasm involving the stomach. "Upon comparing EBV-positive AGS gastric cancer cells and EBV-negative AGS gastric cancer cells, it was demonstrated that EBV-positive AGS cells are characterized by enhanced activity of DNMT3b and higher SSTR1 CpG island methylation levels." (PMID 33085037, 2021). "Moreover, the SSTR1 promotor was frequently methylated in Epstein-Barr virus (EBV) positive primary gastric cancer samples (67%), whereas this was not the case in EBV-negative primary gastric cancer samples." (PMID 33085037, 2021).
neuroendocrine tumors (6 papers, 2015 to 2024). "SSTR1, one of the five somatostatin receptors (SSTRs), plays an important role in neuroendocrine tumors, such as lung carcinoid, and the overexpression of SSTR1 can inhibit cell proliferation." (PMID 33362847, 2020). "For example, the overexpression of somatostatin receptors (SSTR1-5) by neuroendocrine tumors is currently widely used, and when combined with SPECT is the most sensitive localization method so far." (PMID 29674997, 2018). "Thus, the present investigation aimed to determine whether different SSTR (SSTR1, 2A, 3 and 5) and CXCR4 are co-expressed in G1-G3 neuroendocrine tumors and carcinomas by means of immunohistochemistry, using highly specific monoclonal antibodies." (PMID 26259237, 2015).
acromegaly (3 papers, 2021 to 2025). Acromegaly is an acquired disorder related to excessive production of growth hormone (GH) and characterized by progressive somatic disfigurement (mainly involving the face and extremities) and systemic manifestations. "Decreased expression of somatostatin receptors/(SSTR1-5) and dopamine receptors (SSTRs and DRDs), such as DRD4, DRD5, SSTR1, and SSTR2, has been associated with the tumorigenesis of somatotroph adenomas." (PMID 40299639, 2025). "We identified pasireotide as the only FDA-approved drug (a pan-SSTR agonist for treating acromegaly and Cushing disease) with SSTR1 agonist activity and evaluated the potential of repurposing it to overcome ARSI resistance." (PMID 39352383, 2024). "PRDM2, SLC20A1, SSTR1-5, and PR/SET Domain 2 are observed to be involved in the development of somatotroph adenomas." (PMID 40299639, 2025).
breast carcinoma (3 papers, 2006 to 2023). "In human breast cancer cells, SSTR1 and SSTR5 subtypes heterodimerize with epidermal growth factor receptor and modulate the downstream MAPK pathway in an agonist-dependent manner." (PMID 38203605, 2023). "The expression of SSTR subtypes at the levels of mRNA and protein for SSTR1 and -2 has also been reported with the effect of Tamoxifen and estradiol in breast cancer cells." (PMID 38203605, 2023). "In the present study, we compared SSTR1-5 and ErbB1-4 mRNA and protein expression in two breast cancer cell lines: MCF-7 (ER+) and MDA-MB-231 (ERα-)." (PMID 16519802, 2006). "The overexpression of SSTR1 and SSTR4 in MDA-MB-435S breast cancer cells resulted in a decrease in number of cells in the S phase upon receptor activation and associated with cell cycle arrest through dimerization between SSTR1/SSTR4." (PMID 38203605, 2023). "We further anticipate such a possibility of heterodimerization between SSTR1 and SSTR5 and, additionally, between SSTRs and ErbBs in breast cancer cells." (PMID 16519802, 2006). "Using semi-quantitative RT-PCR, we determined SSTR1-5 mRNA expression in MCF-7 (ER+) and MDA-MB-231 (ERα-) human breast cancer cells." (PMID 16519802, 2006). "We have also shown the effects of estradiol and tamoxifen on SSTR1 and SSTR2 expression in breast cancer cells." (PMID 16519802, 2006). "We found higher levels of expression of ErbB1 and lower levels of SSTR1, SSTR4 and ErbB3 in ERα – (MDA-MB-231) cells when compared to ER+ (MCF-7) breast cancer cells." (PMID 16519802, 2006). "Predominant SSTR1 expression and weak SSTR5 expression in breast cancer cells may help explain their poor sensitivity to hormonal therapy." (PMID 16519802, 2006).
colorectal cancer (3 papers, 2016 to 2024). A primary or metastatic malignant neoplasm that affects the colon or rectum. "Hypothesis: SSTR1 cells maintain SCs in a quiescent state, and aberrant SST signaling contributes to SC overpopulation in colorectal cancer (CRC)." (PMID 27927191, 2016).
epilepsy (3 papers, 2011 to 2020). A brain disorder characterized by episodes of abnormally increased neuronal discharge resulting in transient episodes of sensory or motor neurological dysfunction, or psychic dysfunction. "The co-expression network analysis permitted to reveal molecular mechanisms underlying the refractory epilepsy phenotypes, pointing out two potential therapeutic targets represented by the genes SSTR1 and CHRM3." (PMID 22022585, 2011). "Moreover, two candidate genes for therapeutic targeting came out from this analysis: SSTR1, a relevant common hub in febrile and afebrile transcriptomes, and CHRM3, due to its putative role in epilepsy susceptibility development." (PMID 22022585, 2011). "The expression of the subtypes SSTR1 and SSTR2 has been documented in rats in different disease models, such as the epilepsy model." (PMID 29522573, 2018).
Hyperglycemia (3 papers, 2012 to 2021). An increased concentration of glucose in the blood. "Pasireotide that has high affinity for SSTR1, 2, 3 and 5 has been reported to decrease cortisol levels in patients with Cushing’s disease, although this was associated with hyperglycaemia-related adverse events in approximately 75% of patients." (PMID 31935194, 2020). "Similar to the results seen in the insulinoma SCID mouse model, SSTR1/5−/− mice developed temporal hyperglycemia associated with elevated basal glucose levels, lower insulin levels and an abnormal response to IPGTT seven days after the first treatment." (PMID 22905092, 2012). "It has high affinity for SSTR-1, SSTR-2, SSTR-3 and most importantly SSTR-5 and presents hyperglycemia as a common adverse effect, but experience in malignant INSs is very limited." (PMID 34199977, 2021).
insulinomas (3 papers, 2012 to 2023). "The SSTR1/5−/− mouse model was used as the mice represent an immune-competent insulinoma-like mouse model with overexpression of PDX-1 in both acinar cells and islet cells, featured with hyperinsulinemia and hypoglycemia." (PMID 22905092, 2012). "PDX-1 also was overexpressed in mouse insulinoma (β TC-6) cells and in both islet and acinar cells of the pancreata of somatostatin receptor subtypes 1 and 5 knock-out mice (SSTR1/5−/−) (respectively) as compared to that of wild type mice." (PMID 22905092, 2012). "Of the five subtypes of SSTRs (named SSTR1–5), SSTR2 and SSTR5 are most commonly expressed in insulinomas (∼70%)." (PMID 25755880, 2015).
Obesity (3 papers, 2025). Accumulation of substantial excess body fat. "Other GPCRs involved in neurohormonal signalling and associated with obesity and insulin resistance, such as OPRK1 and ADRB2, and receptors for peptide hormones, including somatostatin (SSTR1/2/5) and secretin (SCTR), were also enriched in K cells." (PMID 39441374, 2025). "In summary, BBOX1, SSTR1, MMP7, and LACC1 are identified as diagnostic markers of obesity and NAFLD." (PMID 39619480, 2025). "Obesity and NAFLD share a molecular mechanism with BBOX1, SSTR1, MMP7, and LACC1, which play crucial roles in disease development and can serve as common predictors." (PMID 39619480, 2025). "BBOX1, SSTR1, MMP7, and LACC1 emerged as common predictors for obesity and NAFLD through animal experimentation and predictive model analysis." (PMID 39619480, 2025).
pheochromocytoma (3 papers, 2017 to 2026). "Results revealed that pheochromocytomas and paragangliomas similarly display a predominant SSTR2 and SSTR1 expression regardless of molecular cluster." (PMID 41928014, 2026).